BECN1 (beclin 1)
Diseases named in the same sentence as BECN1 in open-access papers (continued):
Sharing a sentence is not in itself a finding about the gene and the disease.
oral cancer (15 papers, 2015 to 2023). "The present study identified that PL-induced autophagy is associated with autophagy factors, such as p-mTOR, LC3, and Beclin-1, in oral cancer cell lines." (PMID 37760883, 2023). "Overexpression of Beclin 1 resulted in tumor progression in oral cancer, and was associated with poor prognosis." (PMID 26506105, 2015). "In this study, we investigated the expressions of Beclin 1 and Beclin 2 in oral cancer tissues, and examined the associations among expressions of Beclin 1 and Beclin 2, clinicopathologic features, and survival rates." (PMID 26506105, 2015). "The oral cancer tissues exhibited variable cytoplasmic expressions of Beclin 1 and Beclin 2, ranging from total loss to diffuse strong expression." (PMID 26506105, 2015). "Cisplatin-sensitive oral cancer cells exhibit higher miR-30a and lower Beclin 1 (BECN1) expression levels than cisplatin-resistant cells." (PMID 36612314, 2023). "Knockdown of Beclin-1, a marker of autophagy, promotes the proliferation, migration and invasion of primary oral cancer cell lines." (PMID 34897285, 2021). "RelA-mediated Becn1 expression was essential for ROS-induced autophagy in oral cancer cells irradiated by laser." (PMID 33425768, 2020). "Inhibition of autophagy by small molecule inhibitors (SMIs) as well as siRNA silencing of ATG5 and Beclin-1 enhanced apoptosis confirming that nimbolide induced autophagy-dependent apoptosis in oral cancer cells." (PMID 30352996, 2018). "Herein, we found that ROS production is important for the activation of RelA and for BECN1 expression, which in turn induces autophagy in oral cancer cells exposed to LPLI." (PMID 27632526, 2016). "Second, RelA induces BECN1 expression, which induces autophagy in oral cancer cells exposed to LPLI." (PMID 27632526, 2016). "The investigations of Beclin 1 in oral cancer tissues showed that high expression was related to poor prognostic factors and/or aggressive clinical outcomes." (PMID 26506105, 2015). "To investigate the effects of Beclin 1 and Beclin 2 overexpression in oral cancer, we used SAS cells transfected with plasmid expressing flag-tagged Beclin 1 and Beclin 2, respectively." (PMID 26506105, 2015). "To evaluate Beclin 1 and Beclin 2 expressions and their subcellular localization, we performed immunohistochemistry on 195 cases of oral cancer tissues and normal oral mucosas." (PMID 26506105, 2015). "Only a small subset of oral cancer tissues expresses nuclear staining of Beclin 1 (33/195, 16.92%) and Beclin 2 (29/195, 14.87%)." (PMID 26506105, 2015). "In oral cancer cells, overexpression of either Beclin 1 or Beclin 2 led to autophagy activation and increased clonogenic survival; knockdown of Beclin 2 impaired autophagy and increased clonogenic survival." (PMID 26506105, 2015). "We investigated Beclin 1 and Beclin 2 expressions by immunohistochemistry in 195 cases of oral cancer." (PMID 26506105, 2015). "Relationships between Beclin 1 and Beclin 2 expressions and clinicopathologic variables in 195 cases of oral cancer." (PMID 26506105, 2015). "The aims of this study were to analyze Beclin 1 and Beclin 2 expressions in oral cancer tissues and in cell lines, and to evaluate their possible roles in cancer progression." (PMID 26506105, 2015). "The specific roles of RelA and BECN1 on the process of autophagy in oral cancer cells irradiated with LPLI remain unclear." (PMID 27632526, 2016). "Moreover, reactive oxygen species (ROS) production was induced, which increased RelA transcriptional activity and beclin 1 (BECN1) expression in oral cancer cells irradiated with LPLI." (PMID 27632526, 2016). "Moreover, the levels of phosphorylated RelA/p65 at Ser536 (RelA S536-P), a primary active component in the canonical NF-κB pathway, and BECN1 expression were elevated in LPLI-treated oral cancer cells." (PMID 27632526, 2016). "The cytoplasmic Beclin 1 and Beclin 2 expressions were unrelated in oral cancer tissues." (PMID 26506105, 2015).
oral cancer (continued). "Knockdown of RelA significantly suppressed the elevation in BECN1 and MAP1LC3 expression and the ratio of MAP1LC3-II/I in the cells exposed to LPLI, suggesting that LPLI may trigger ROS production and activate RelA, thereby turning on BECN1 expression and inducing autophagy in oral cancer cells." (PMID 27632526, 2016). "Because the Akt/mTOR pathway is known to negatively regulate autophagosome formation, we next examined the correlation of NEDD8 expression with the protein levels of autophagosome components, e.g., Beclin-1, Atg5 and LC3-I/II, in oral cancer cells." (PMID 36890567, 2023). "The LC3B-I protein levels remined constant, beclin 1 protein levels declined and the LC3B-II protein levels increased in miR-1179 inhibitor transfected SCC-9 and SCC-25 oral cancer cells." (PMID 32809144, 2020). "Our study was consistent with previous researches, and we further revealed that overexpression of Beclin 1 in SAS induced tumor growth in clonogenic assay, demonstrating its role of tumor progression in oral cancer." (PMID 26506105, 2015). "Therefore, analysing the difference between the expressions of Beclin-1 and mTOR in OLK is helpful to determine the process of occurrence and malignant transformation of oral carcinoma." (PMID 38223571, 2023). "Moreover, increased expressions of Beclin-1, Atg3, Atg5, Atg7, Atg12, Atg 16, LC3-I, and LC3-II proteins indicated that 4-carbomethoxyl-10-epigyrosanoldie E triggered autophagy in oral cancer cells." (PMID 36275891, 2022).
osteoarthritis (15 papers, 2012 to 2025). A noninflammatory degenerative joint disease occurring chiefly in older persons, characterized by degeneration of the articular cartilage, hypertrophy of bone at the margins and changes in the synovial membrane. "For instance, Atg5, Atg7, and Beclin 1 are down‐regulated in the normal aging brain, whereas, in osteoarthritis, the levels of ULK1, Beclin 1, and LC3 fall." (PMID 36539927, 2023). "In vivo results showed that SND1 silencing inhibited SND1, PINK1 and BECN1 proteins expression in rat knee cartilage tissues compared with the osteoarthritis rats." (PMID 37749650, 2023). "Tat-BECN1 attenuates extracellular matrix degradation in osteoarthritis chondrocytes and ameliorates cartilage degeneration in rodent osteoarthritis model." (PMID 36172279, 2022). "Suppression in the expression (western blot) of Beclin-1 and LC3 is due to the damage caused by osteoarthritis." (PMID 35035830, 2022). "This applies, for instance, to normal human brain aging (in which Atg5, Atg7, and Beclin 1 are down-regulated), insulin resistance and metabolic syndrome, or osteoarthritis (in which Ulk1, Beclin 1, and LC3 are down-regulated)." (PMID 24710479, 2012). "In a destabilization of the medial meniscus (DMM)-induced mouse osteoarthritis model, tissue immunofluorescence technique similarly indicated a decrease in chondrocyte autophagic activity in OA, including ATG7, Beclin-1, and LC3." (PMID 41013182, 2025). "This study demonstrates that a therapeutic-grade exosome formulation can alleviate osteoarthritis by restoring the balance between autophagy and apoptosis through modulation of the BCL2–Beclin-1 signaling axis." (PMID 41351157, 2025). "We then performed immunofluorescence staining and investigated that the levels of autophagy (Beclin‐1, LC3B), apoptosis (cleaved caspase‐3) and p‐AMPK in osteoblasts (osterix) were significantly higher in SONFH than in osteoarthritis patients." (PMID 34612603, 2021).
acute kidney injury (14 papers, 2021 to 2025). Sudden and sustained deterioration of the kidney function characterized by decreased glomerular filtration rate, increased serum creatinine or oliguria. "In addition, upregulation of ALDH2 can regulate autophagy to protect renal tubular epithelial cells through the Beclin-1 pathway, thereby ameliorating acute kidney injury and neuronal damage caused by hypoxia." (PMID 38609879, 2024). "In addition, endogenous Beclin-1 expression was found to be protective against acute kidney injury (AKI) by attenuating damage, promoting tubular cell proliferation, and reducing fibrosis." (PMID 40529491, 2025). "In a mouse model of acute kidney injury, a forced expression of a gain-of-function mutant form of Beclin-1, and specifically proximal tubular Beclin-1 expression, resulted in decreased fibrosis 14 days post-injury indicating a possible protective effect against IR injury." (PMID 36875088, 2023). "Consistently, Dex can upregulate the expression of autophagy and mitophagy related proteins, such as Beclin-1, LC3 II and PINK1, and thus enhances autophagy, resulting in the removal of damaged mitochondria in lipopolysaccharide (LPS)-induced acute kidney injury." (PMID 34772407, 2021).
colitis (14 papers, 2016 to 2026). Inflammation of the colon. "Herbal prescription Jianpi Qingchang Decoction significantly reduced LC3 and Beclin 1 protein expression and improved colitis in DSS-induced UC mice." (PMID 36081930, 2022). "Since Becn1 −/− mice developed colitis, we characterized the lamina propria lymphocytes to examine the characteristics of T cells." (PMID 32984329, 2020). "Research has demonstrated decreased expressions of LC3II/I and beclin 1 in colitis." (PMID 40534879, 2025). "Additionally, resveratrol is able to modulate autophagy in colitis by reducing expression of its mediators including beclin-1." (PMID 40359212, 2025). "Hence, Hy-Ex upregulates LC3II/I and beclin 1, making it a potential candidate for preventing colitis." (PMID 40534879, 2025). "To further explore the impact of the Xianhecao-Huanglian drug combination on autophagy in DSS-induced IBD mice, we examined the expression of proteins associated with autophagy, including ATG12, Beclin-1, LC3A/B, and p62, in colitis tissues using Western blot analysis." (PMID 39187810, 2024). "β-hydroxybutyrate may also enhance autophagy as revealed by reduced p62 and increased BECN1, which may help resolve gut inflammation in colitis." (PMID 37513865, 2023). "By potentially enhancing autophagy through reducing p62 and increasing BECN1, β-hydroxybutyrate may help resolve gut inflammation in colitis." (PMID 37513865, 2023). "As the results of ANOVA indicate, only time elapsed after TNBS administration had a significant effect on the reduction of LC3-II expression, while the induction of inflammation had a significant effect on Beclin-1 expression with a higher expression observed in the colitis group (ANOVA, p < 0.05)." (PMID 33499397, 2021). "This suggested that the Becn1 −/− mice developed severe colitis." (PMID 32984329, 2020). "Also, as mice grew older, Becn1 −/− mice progressively lost weight and developed severe colitis." (PMID 32984329, 2020). "In this work, blocking of α7nAChR by MLA in ANI/NEO treated colitis mice, the levels of LC3-II/LC3-I ratio and Beclin-1 were decreased and the P62 was increased, suggeting that α7nAChR mediates the role of ANI/NEO on promoting autophagy in DSS-induced mice." (PMID 38354108, 2024). "HLD-DS reduced p-NF-κB p65, LC3II/I, and Beclin 1 expression, which suggested that HLD alleviated colitis by inhibiting the NF-κB pathway and autophagy." (PMID 36081930, 2022). "In the same vein, in DSS-induced mice, treatment with curcumin-enriched polyphenolics ameliorated colitis by impeding excessive autophagy and reducing the mRNA and protein expression of autophagy-related 5, LC3-phosphatidylethanolamine conjugate, and beclin-1 in colonic tissue." (PMID 40359212, 2025). "In addition, treatment with HU 308 also significantly increased the LC3-II/LC3-I ratio and Beclin-1 and decreased SQSTM1 in colon from DSS-induced colitis mice." (PMID 27611972, 2016). "Besides elevating the LC3-II/LC3-I ratio, ATG5 and Beclin-1 levels and decreasing P62 level, the ANI/NEO combination decreased the expression of several inflammatory cytokines (INF-γ, TNF-α, IL-6, and IL-22) in colon tissue from mice with DSS-induced colitis." (PMID 38354108, 2024). "Therefore, it can be concluded that the colitis group fed with feed without beta-glucans had the highest expression of Caspase-3 and Beclin-1, while the lowest expression of both these proteins was observed in the control groups." (PMID 33499397, 2021). "No colitis was observed in 2D2.WT and 2D2.Becn1 −/− mice for at least 8 months of age." (PMID 32984329, 2020).
COVID-19 (14 papers, 2020 to 2026). A disease caused by infection with severe acute respiratory syndrome coronavirus 2. "In addition, the increase in beclin-1 serum levels was associated with severe inflammation in COVID-19, and the suppression of autophagy in leukocytes of severely ill COVID-19 patients correlated with impaired antigen presentation and T cell activation." (PMID 37174682, 2023). "Our study showed that the levels of vitamin D and two autophagy markers (ATG7 and BECN1) were lower in patients with severe/critical COVID-19 than in those with mild/moderate COVID-19." (PMID 38783947, 2024). "Our partial correlation analysis showed that vitamin D had strong positive correlations with two autophagy markers (ATG7 and BECN1), suggesting a close link between vitamin D and autophagy in COVID-19." (PMID 38783947, 2024). "Plasma ACBP concentrations positively correlated with ATG 3, ATG5 and LC3II, but negatively correlated with ATG4B, BECN1 and galectin 8 in participants with COVID-19." (PMID 39835130, 2024). "The group with severe/critical COVID-19 had more abnormalities in many laboratory indicators, including lower levels of autophagy markers (BECN1 and ATG7) and vitamin D, and higher levels of inflammatory markers (TNF-α and IL-1β)." (PMID 38783947, 2024). "We next assessed the levels of key autophagy markers p62, LC3, ATG5, and beclin-1 in the blood of healthy controls and COVID-19 patients at admission and one week later." (PMID 37174682, 2023). "The blood levels of proautophagic beclin-1 were increased, while the expression of LC3 mRNA and LC3-I/II conversion in blood mononuclear cells were reduced in COVID-19 compared to control subjects." (PMID 37174682, 2023). "Therefore, BECN1 could be used as another COVID-19 marker to determine the severity of the disease." (PMID 34440791, 2021). "This may have directional significance for the new therapeutic modalities in the treatment of COVID-19 and allow us to further investigate the effects of UPR on FIP200-Beclin-1 axis activation and viral replication to combat the virus." (PMID 34960736, 2021). "Finally, in clinical studies of COVID-19 patients, serum levels of autophagic proteins, such as LC3, SQSTM1, and BECN1, predicted the severity of COVID-19 disease." (PMID 34440791, 2021).
Hepatic steatosis (14 papers, 2016 to 2025). Steatosis is a term used to denote lipid accumulation within hepatocytes. "Quantitative immunohistochemistry conducted on human liver allograft biopsies showed that, the reduction of autophagy markers LC3 and Beclin-1 at 1 h after reperfusion, was correlated with hepatic steatosis and poor survival of liver transplant recipients." (PMID 27077802, 2016). "Additionally, both energy restriction and resveratrol treatment have been shown to stimulate autophagy in hepatic steatosis via a significant augmentation of autophagy-related proteins, including Beclin-1." (PMID 40529491, 2025). "To confirm whether the ameliorative effects of G-CSF on hepatic steatosis were associated with autophagy, we examined the protein expression of autophagy markers, including LC3, beclin-1, and p62 by Western blotting." (PMID 32775312, 2020). "Also, the increased level of LC3 and Beclin 1 protein was detected in cafeteria (CAF) diet-fed WIST rats treated with bergamot polyphenol fraction (BPF) during the reduce of hepatic steatosis and total lipid content." (PMID 32948162, 2020). "Both expression of MAP1LC3A and Beclin 1 in patient is exhibited much lower in immunostaining and Western blotting but not vanished indicating possible tendency of lipophagy in development of fatty liver disease." (PMID 32280452, 2020). "A recent study revealed that autophagy activation following treatment with a polyphenol fraction could prevent nonalcoholic hepatic steatosis by upregulation of autophagy markers, such as beclin-1, and LC3 conversion with decreased p62 levels in the liver tissue of rats fed a cafeteria diet." (PMID 32775312, 2020). "DHM treatment elevated Beclin 1, ATG 5, and LC3-II levels in hepatic steatosis models, correlating with autolysosome formation." (PMID 38532480, 2024). "The expression of the Beclin-1 and LC3 genes was examined using real-time PCR to evaluate the impacts of Que-metformin on the autophagy induction in the hepatic steatosis model of HepG2 cells." (PMID 38116565, 2023). "Also, resveratrol and akebia saponin D prevent hepatic steatosis, accompanied with up-regulation of autophagy markers such as LC3-II, Beclin 1 and p62." (PMID 32948162, 2020). "The mechanism of trehalose action in the attenuation of hepatic steatosis in apoE−/− mice on an HFD seems to be at least partially related to autophagy induction, as evidenced by the significant increase in key proteins related to autophagy in the liver: LC3, Beclin-1, and APG7." (PMID 30925684, 2019).